LRTOMT (leucine rich transmembrane and O-methyltransferase domain containing)
Synonyms: COMT2; CFAP111; LRTOMT1; LRTOMT2; DFNB63; LRRC51; LRRC51-TOMT
Gene: Protein-coding gene on chromosome 11 (72,080,331 to 72,110,782, forward strand). Ensembl gene ENSG00000284922.
Pathways (Reactome):
Neuronal System: Enzymatic degradation of dopamine by COMT
Gene Ontology:
Molecular function: catechol O-methyltransferase activity; O-methyltransferase activity
Biological process: auditory receptor cell development; catecholamine catabolic process; developmental process; dopamine catabolic process; dopamine metabolic process; sensory perception of sound
Cellular component: cytoplasm; endoplasmic reticulum; plasma membrane; membrane
Genetic constraint (gnomAD): Loss-of-function variants: 27 observed, 28.31 expected, observed/expected ratio (o/e) 0.95, 90% interval 0.7 to 1.32. The upper end of that interval is the gene's LOEUF score, 1.32, which puts it in group 5 of 6, group 1 being the genes least tolerant of losing a copy. Missense variants: 368 observed, 378.51 expected, observed/expected ratio (o/e) 0.97, 90% interval 0.89 to 1.06. Synonymous variants: 146 observed, 159.03 expected, observed/expected ratio (o/e) 0.92, 90% interval 0.8 to 1.05.
Gene-disease validity (ClinGen):
ClinGen rates the evidence that LRTOMT causes each of these diseases.
autosomal recessive nonsyndromic hearing loss 63 (autosomal recessive): Definitive. Any autosomal recessive nonsyndromic deafness in which the cause of the disease is a mutation in the LRTOMT gene.
Diseases named in the same sentence as LRTOMT in open-access papers:
LRTOMT is named in the same sentence as 6 diseases in open-access papers, as found by Europe PMC text mining. Sharing a sentence is not in itself a finding about the gene and the disease. The quoted sentences say what the papers report.
deafness (6 papers, 2011 to 2019). An inherited or acquired condition characterized by the complete loss of the ability to hear from one or both ears. "All seven of these families have variants in seven different known deafness genes, LRTOMT, LHFPL5, TMPRSS3, OTOF, MYO15A, ESRRB, and KCNE1." (PMID 31835641, 2019). "Defects in this process are likely mechanistically linked to deafness caused by mutations in LRTOMT/Tomt." (PMID 28504928, 2017). "In this regard, mutations of either LRTOMT or FGF3 should be considered when incompletely characterized nonsyndromic deafness is found to be linked to genetic markers of the DFNB63 locus on chromosome 11q 13.2 -q13.3." (PMID 21306635, 2011). "However, the findings presented here suggest that defects in the assembly and transport of the mechanotransduction machinery of hair cells are likely intricately linked to the mechanism by which mutations in Tomt in mice and LRTOMT in humans cause deafness." (PMID 28504928, 2017). "However, the mechanisms by which mutations in LRTOMT and Tomt cause deafness are currently unknown and the extent to which catecholamines play a role in this process remains to be established." (PMID 28504928, 2017). "Mutations in the LRTOMT gene, which encodes a protein with homology to the catecholamine methyltransferase COMT that is linked to schizophrenia, cause deafness." (PMID 28504928, 2017). "Some but not all the mutations in the human LRTOMT gene that cause deafness are also predicted to affect methyltransferase activity, although this has so far not been demonstrated experimentally." (PMID 28504928, 2017). "We conclude that LRTOMT mutations have no role in causing sporadic deafness in the studied population." (PMID 24551789, 2013). "The biallelic sequence variants predicted to be the causative mutations in the patients are all located in genes already known to be involved in deafness (MYO15A, TMC1 and LRTOMT), but these particular mutations have not been previously reported." (PMID 24926664, 2014).
non-syndromic deafness (1 paper, 2017). "Transmembrane O-methyltransferase (TOMT/LRTOMT) is responsible for non-syndromic deafness DFNB63." (PMID 28534737, 2017).
LRTOMT also shares sentences with these, for which no sentence is quoted: hearing loss (4 papers); postmenopausal osteoporosis (1); schizophrenia (1); syndromic (1).